OPA1 (OPA1 mitochondrial dynamin like GTPase)
Diseases named in the same sentence as OPA1 in open-access papers (continued):
Sharing a sentence is not in itself a finding about the gene and the disease.
Encephalopathy (5 papers, 2016 to 2023). Encephalopathy is a term that means brain disease, damage, or malfunction. "In our Knowledge, cardiac involvement in patients carrying OPA1 mutation has only been recently reported for the first time in two sisters harboring a homozygous OPA1 mutation leading to lethal encephalopathy and hypertrophic cardiomyopathy." (PMID 27723783, 2016). "Interestingly, cardiac involvement in patients carrying OPA1 mutation has been reported for the first time in two patients harboring a homozygous recessive OPA1 mutation leading to a fatal encephalopathy with progressive hypertrophic cardiomyopathy." (PMID 34177786, 2021). "Our report confirms the broad complexity in the phenotypic spectrum associated with recessive OPA1 mutations that ranges from non-syndromic phenotypes overlapping with those caused by dominant OPA1 mutations to severe fatal encephalopathy resembling typical mitochondrial diseases." (PMID 28494813, 2017). "Three patients, instead, had alterations of nuclear genes associated with mitochondrial diseases (one PEO patient involving POLG1 and two patients involving OPA1 and suffering from Encephalopathy and Polyneuropathy)." (PMID 37763097, 2023).
Hepatic steatosis (5 papers, 2018 to 2023). Steatosis is a term used to denote lipid accumulation within hepatocytes. "Notably, GDF15 partially mediates the resistance to DIO, but is necessary for the improvement in glucose homeostasis and hepatic steatosis following high-fat feeding in OPA1 BKO mice." (PMID 37819027, 2023). "Furthermore, we also unveiled a role for GDF15 in attenuating DIO and improving glucose clearance and hepatic steatosis in OPA1 BKO mice." (PMID 37819027, 2023). "The protection against diet-induced hepatic steatosis present in OPA1 BAT KO and OPA1/FGF21 BAT DKO mice was no longer observable in the absence of ATF4 induction in OPA1 BAT KO mice." (PMID 33944779, 2021).
ischemic stroke (5 papers, 2022 to 2023). A stroke disorder caused by obstruction of blood flow to the brain, due to thrombotic (local blood clot formation) or embolic (due to a blood clot or other material traveling from another site) event. "OPA1 has been identified as a promising gene for research in adipose tissue, ischemic stroke, prion diseases and so on, and its overexpression has been shown to improve mitochondrial dysfunction." (PMID 37434203, 2023). "Exercise preconditioning can alleviate the brain edema and improve the neurological deficit after ischemic stroke through facilitating the expression of OPA1 and mitochondrial complex II/III/IV closely related to ATP generation." (PMID 35571256, 2022). "The OPA1 can reduce brain oedema in ischaemic stroke, besides, its expression increased after exercise." (PMID 35040556, 2022). "Together, all studies suggest that OPA1 is a potential target for treatment of ischemic stroke." (PMID 35571256, 2022).
liver cancer (5 papers, 2020 to 2023). An epithelial or non-epithelial malignant neoplasm that arises from the liver. "The OPA1 gene encodes the optic atrophy 1 protein, a dynamin GTPase involved in mitochondrial fusion and its knockdown in liver cancer inhibited tumour growth in mice." (PMID 35821197, 2022). "To obtain insight in the potential mechanisms that mediate acceleration of tumor cell growth by mitochondrial fusion in liver cancer, we performed genome-wide transcriptomic analysis by RNA sequencing in OPA1 knockdown Huh7." (PMID 31947947, 2020). "OPA1 and MFN1 are upregulated in ovarian, breast, liver cancer, AML, esophageal, renal, and stomach cancer, and another RNAseq data have also stressed the significant mRNA overexpression of OPA1 in a variety of tumor types, including breast, renal, stomach, and esophageal cancer." (PMID 38156294, 2023).
neuroblastoma (5 papers, 2016 to 2024). Neuroblastoma (NB) is the most common solid, extracranial childhood tumor. "An in vitro study also suggested that silybin treatment protects human neuroblastoma SH-SY5Y cells from H2O2-induced mitochondrial damage by regulating OPA1 and Drp1 protein expression." (PMID 38539857, 2024). "The same group provided further evidence that overexpression of APP in M17 neuroblastoma cells results in predominant mitochondrial fragmentation and decreased levels of Drp1 and OPA1, while overexpression of Drp1 or OPA1 could partially rescue some of these defects." (PMID 26903809, 2016). "Decreased OPA1 has been noted in the M17 human neuroblastoma line, overexpressing wild type APP, although OPA1 and the mitofusins were found to be increased in HEK293 cells, an embryonic kidney cell line, when human tau was overexpressed." (PMID 33440662, 2021). "As discussed by the authors, KIF1Bβ, which is frequently deleted in neuroblastoma, physiologically interacts with YME1L1, a mitochondrial protease, favoring OPA1 cleavage and mitochondrial fission." (PMID 33233365, 2020).
normal tension glaucoma (5 papers, 2009 to 2024). "Variants of OPA1 have been associated with normal-tension glaucoma in Japanese and Caucasian populations." (PMID 39456800, 2024). "To date, no meta-analysis has been conducted to validate the association of polymorphisms of OPA1 with normal tension glaucoma (NTG) and high tension glaucoma (HTG)." (PMID 22879959, 2012). "To better understand the exact consequence of the relationship between OPA1 polymorphisms and normal tension glaucoma susceptibility, we investigated the effects of the OPA1 IVS8+4C>T and IVS8+32T>C genotypes on the occurrence of NTG by ethnicity." (PMID 22879959, 2012). "In conclusion, the results of this meta-analysis suggest that two OPA1 polymorphisms [IVS8+4C>T (rs166850) and IVS8+32T>C (rs10451941)] are associated with an increased risk for normal tension glaucoma." (PMID 22879959, 2012). "Certain OPA1 polymorphisms have been described in association with an increased risk of developing POAG or normal tension glaucoma in some, but not all, populations studied." (PMID 21552501, 2011). "Results suggested that genetic variation in five of the candidate genes (RDX, SNX16, OPA1, SOD2 and CYP1B1) is unlikely to confer major risk to develop normal tension glaucoma in the German population." (PMID 19754948, 2009).
optic atrophy type 1 (5 papers, 2013 to 2025). "We report two novel splice region mutations in OPA1 in two unrelated families presenting with autosomal-dominant optic atrophy type 1 (ADOA1) (ADOA or Kjer type optic atrophy)." (PMID 28245802, 2017). "Why OPA1 gene mutations only impact the eyes in people with optic atrophy type 1 but have more significant effects in ADOA-plus syndrome is unknown." (PMID 36980899, 2023). "Mutations in OPA1 have been associated with optic atrophy type 1." (PMID 36611869, 2022). "This upregulated miR-208a-5p directly targeted the 3'-UTR of OPA1 (optic atrophy type 1), suppressing mitophagic activity." (PMID 40547022, 2025). "Forty-three participants were diagnosed with multiple mtDNA deletions (unspecified nuclear genetic defect, OPA1 (optic atrophy type 1), POLG1 (polymerase gamma) and PEO1 (Twinkle))." (PMID 23433484, 2013).
retinal degeneration (5 papers, 2010 to 2022). Degeneration of the retina. "In a murine model of DOA, caused by mutation c.2708_2711delTTAG in Opa1 gene, IVT injection of AAV2 carrying the human OPA1 cDNA under the control of the cytomegalovirus promoter resulted in the prevention of retinal degeneration." (PMID 36471396, 2022). "Consistent with the PINK1 and Parkin results, the severity of retinal degeneration was alleviated by Drp1 overexpression and enhanced by Opa1 overexpression in 5-day-old TrpP365 flies." (PMID 27054334, 2016).
type 2 diabetes (5 papers, 2014 to 2025). "In the type 2 diabetic mouse model, db/db mice, Opa1 levels were significantly reduced in mitochondria of pancreatic islets compared with those of non-diabetic mice." (PMID 34072974, 2021). "Type II diabetes increases the protein level of liver rhythm molecule CLOCK and impairs the mitochondrial morphology, dynamics (OPA1 and Fis1), and mitophagy, which can be optimized by two differently timed exercises." (PMID 36012573, 2022). "Finally, in humans with type 2 diabetes it was shown that protein levels of both MFN2 and OPA1 were reduced in skeletal muscle compared with obese control individuals." (PMID 33258025, 2021).
cerebral infarction (4 papers, 2015 to 2022). An ischemic condition of the brain, producing a persistent focal neurological deficit in the area of distribution of the cerebral arteries. "Our results indicate that mild OPA1 overexpression is compatible with life and protects mice from multiple form of damage, implicating cristae remodeling in myocardial and brain infarction, hepatocellular apoptosis, and muscular atrophy." (PMID 26039448, 2015). "Thus, mild overexpression of OPA1 protects mice from multiple forms of damage, including cristae remodeling in myocardial and cerebral infarction, hepatocellular apoptosis and muscle atrophy." (PMID 36139798, 2022).
glioma (4 papers, 2020 to 2024). A benign or malignant brain and spinal cord tumor that arises from glial cells (astrocytes, oligodendrocytes, ependymal cells). "To further validate that hsa-mir-497_25g repressed OPA1 and VAPB, we transfected p497_25g into two glioma cell lines, i.e., U-118-MG and Hs683, and examined the expression levels of OPA1 and VAPB with quantitative RT-PCR (qRT-PCR) experiments." (PMID 36611869, 2022). "YME1L silencing or KO resulted in reduction of TIMM44-dependent mitochondrial genes, including Opa1, Mfn1 and Mfn2, in P1 glioma cells." (PMID 36438483, 2022). "In fact, chromosome 3q26 gene products SRY-Box Transcription Factor 2 (SOX2) and OPA1 were found to be differentially regulated in invasive gliomas." (PMID 33233365, 2020). "Strikingly, they found that OPA1 inactivation increased LN319 glioma cell invasion in vitro, and boosted cell dispersion in xenotransplanted Danio rerio embryos." (PMID 33233365, 2020). "Furthermore, overexpression of METTL3 up-regulated DRP1 and p-DRP1 proteins in both glioma cell cytoplasm and mitochondria while down-regulating OPA1 and MFN2 proteins." (PMID 38405130, 2024). "In glioma cell cytoplasm, overexpression of MIF suppressed DRP1 and p-DRP1 expression while enhancing OPA1 and MFN2 expression." (PMID 38405130, 2024). "Opa1, Mfn1 and Mfn2, TIMM44-dependent mitochondrial genes, were increased in TIMM44-overexpressed P1 glioma cells." (PMID 36438483, 2022). "We also demonstrated that overexpression of A-to-I edited miR-497-5p downregulated the expression of OPA1 and VAPB, and repressed proliferation of glioma cells." (PMID 36611869, 2022). "mRNA expression of TIMM44-dependent mitochondrial genes, including Opa1, Mfn1 and Mfn225, were dramatically decreased with TIMM44 silencing or KO in P1 glioma cells." (PMID 36438483, 2022). "This study confirmed that LINC00475-S could promote mitochondrial fission in glioma cells by increasing DRP1 and p-DRP1 levels while down-regulating OPA1 and MFN2 expression." (PMID 38405130, 2024). "Furthermore, overexpression of A-to-I edited miR-497-5p downregulates OPA1 and VAPB in two cell lines, and inhibits proliferation of glioma cells." (PMID 36611869, 2022). "In the mitochondria of glioma cells, MIF overexpression markedly inhibited DRP1 and p-DRP1 expression while increasing OPA1 levels, with no substantial impact on MFN2 expression." (PMID 38405130, 2024).
Hearing impairment (4 papers, 2021 to 2026). A decreased magnitude of the sensory perception of sound. "The influence of combined OPA1 and PARL mutations on the development of hearing defects in patients with ADOA warrants further investigation." (PMID 34573359, 2021).
hypertrophic cardiomyopathy (4 papers, 2016 to 2022). A condition in which the myocardium is hypertrophied without an obvious cause. "The fatal multisystemic manifestations observed further extend the complex phenotype associated with pathogenic OPA1 mutations, in particular the previously unreported association with hypertrophic cardiomyopathy." (PMID 26561570, 2016). "We have further extended the mutational and phenotypic spectrum of OPA1 disease to include lethal infantile mitochondrial encephalomyopathy and hypertrophic cardiomyopathy secondary to a novel homozygous missense mutation that targets the key functional GTPase domain." (PMID 26561570, 2016). "Second, hypertrophic cardiomyopathy has not been reported previously to be associated with human OPA1 mutations." (PMID 26561570, 2016).
leukemia (4 papers, 2020 to 2025). A malignant (clonal) hematologic disorder, involving hematopoietic stem cells and characterized by the presence of primitive or atypical myeloid or lymphoid cells in the bone marrow and the blood. "Dysregulated mitochondrial dynamics, including OPA1-mediated fusion, are observed not only in AML but also in other leukemias." (PMID 41357210, 2025). "We significantly depleted MFN2 or OPA1 in PDX samples, which resulted in shorter mitochondria as measured by confocal imaging, and to a significant reduction of leukemia colony formation (L-CFU)." (PMID 36739349, 2023). "Interestingly, a survey on the Leukemia MILE Dataset shows that T-ALL primary cells express lower mRNA levels of Bcl2l11 (Bim) compared with healthy bone marrow control tissue while Dnm1l (Drp1), Opa1 and Bcl2 levels do not vary." (PMID 32346136, 2020).
Mitochondrial myopathy (4 papers, 2009 to 2025). "Deletion of FGF21 in OPA1‐deficient mice, a model of mitochondrial myopathy, resulted in partial attenuation of muscle wasting and prolonged survival." (PMID 39976232, 2025). "We found that DNJ targeted nuclear-encoded OPA1 to function as a mitochondrial rescue agent, showing the therapeutic potential of our mitochondrial hypertrophic cardiomyopathy and even other mitochondrial diseases, such as hearing loss, mitochondrial myopathy, or Leigh syndrome." (PMID 37200096, 2023). "Deletion of FGF21 appeared to be beneficial in alleviating the disease condition in OPA1 KO mice, a model of mitochondrial myopathy." (PMID 39976232, 2025). "Third, in other mitochondrial diseases, such as myoclonus epilepsy associated with ragged-red fibers (MERRF), mitochondrial myopathy, encephalopathy, lactic acidosis and stroke-like episodes (MELAS), mitochondrion are fragmented which is associated with proteolytical processing of OPA1." (PMID 19718456, 2009).
myopia (4 papers, 2009 to 2025). "Moreover, a recent genome-wide linkage study followed by a fine-scale association mapping identified a myopia susceptibility gene locus containing the PARL gene which inhibits the mitochondrial pathway of apoptosis by interaction with OPA1." (PMID 19779542, 2009).
ophthalmoplegia (4 papers, 2009 to 2023). Weakness or paralysis of at least one of the muscles controlling the movement of the eye. "Indeed, it has been reported that OPA1 mutations are also associated with ptosis and ophthalmoplegia." (PMID 19718456, 2009).
preeclampsia (4 papers, 2017 to 2022). Preeclampsia is a hypertensive disorder of pregnancy that is characterized by new-onset hypertension with proteinuria presenting after 20 weeks of gestation, and depending on mild or severe forms may initially present with severe headache, visual disturbances, and hyperreflexia. "On the other hand, an increase in OPA1 has been suggested as a compensatory mechanism for increased mitochondrial content in preeclampsia, potentially by the stabilization of mitochondrial structures." (PMID 34679654, 2021). "Pro-fusion mitochondrial dynamin like GTPase (OPA1) expression was affected by gestational age and interaction of preeclampsia/gestational age." (PMID 30455461, 2018). "In the myometrium of the early-onset preeclampsia group OPA1 and Bcl-2 were up-regulated compared to those of the control (p < 0.05)." (PMID 28736722, 2017).
prion disease (4 papers, 2019 to 2025). A transmissible disease that is caused by a protein that is able to induce abnormal folding of normal cellular proteins, leading to characteristic spongiform brain changes, which are associated with neuronal loss without an inflammatory response. "Our work indicates that overexpression of OPA1 alleviates mitochondrial damage in prion diseases by preventing mitochondrial network fragmentation, disorganization of cristae structure, mtDNA loss, mitochondrial dysfunction, and cell death." (PMID 31551424, 2019). "In summary, these results indicate that OPA1 is a crucial factor in mtDNA depletion in prion diseases." (PMID 31551424, 2019). "We will further study the impact of OPA1 overexpression on respiratory chain in prion disease models." (PMID 31551424, 2019). "In this study, we observed downregulation of OPA1 in prion disease models in vitro and in vivo, mitochondria structure damage and dysfunction, loss of mtDNA, and neuronal apoptosis." (PMID 31551424, 2019). "To search for other mitochondrial fusion proteins involved in mitochondrial network fragmentation and mitochondrial dysfunction in prion diseases, in this study we investigated the expression of mitochondrial fusion-regulating proteins, OPA1, MFN1, and MFN2." (PMID 31551424, 2019). "Silencing of OPA1 aggravates mitochondrial network fragmentation, whereas overexpression of OPA1 rescues mitochondrial network morphology in the in vitro model of prion diseases." (PMID 31551424, 2019). "Our results demonstrated that overexpression of OPA1 alleviates prion-associated mitochondrial network fragmentation and cristae remodeling, mitochondrial dysfunction, mtDNA depletion, and neuronal apoptosis, suggesting that OPA1 may be a novel and effective therapeutic target for prion diseases." (PMID 31551424, 2019). "Our research shows that the protein level of OPA1 is dramatically downregulated in in vitro and in vivo models of prion diseases, and OPA1 overexpression alleviated PrP106–126-induced mitochondrial cristae collapse, mtDNA depletion, mitochondrial dysfunction, and neuronal apoptosis." (PMID 31551424, 2019). "Taken together, OPA1 is downregulated in prion disease models in vivo and in vitro." (PMID 31551424, 2019). "Our results indicate that OPA1 may be another potential therapeutic target of prion diseases." (PMID 31551424, 2019). "To further investigate the role of melatonin and mitochondrial dynamic proteins in prion diseases, we measured DRP1 and OPA1 expression in N2A cells treated with PrP106-126 and a DRP1 inhibitor, Mdivi-1 and in N2a cells overexpressing OPA1." (PMID 32526704, 2020).
sensorineural deafness (4 papers, 2015 to 2022). "In previous studies we characterized sensorineural deafness in patients harboring missense mutations in the OPA1 gene." (PMID 31191217, 2019). "Besides optic atrophy, sensorineural hearing loss is the earliest and most frequent clinical feature associated with OPA1 missense mutations." (PMID 31191217, 2019). "S07, who had an OPA1 variant, was reclassified as autosomal DOA with sensorineural deafness and type 1 DM and was excluded from this group for genotype–phenotype analysis." (PMID 34006618, 2022). "The genetic basis of DOA not linked to OPA1 mutations is increasingly being elucidated, and a growing list of other genes involved in the recurrent association of syndromic DOA and sensorineural deafness is being reported." (PMID 31191217, 2019).
Spastic paraplegia (4 papers, 2009 to 2023). Complete loss of the ability to move the lower limbs accompanied by spasticity of the lower limbs. "Yet, optic atrophy is found associated with spastic paraplegia linked to recessive mutations in SPG7, the paralog of AFG3L2 encoding another component of the m-AAA protease involved in OPA1 proteolytic maturation." (PMID 26539208, 2015).